RBP2 (retinol binding protein 2)
Description:
Intracellular transport of retinol.
Synonyms: CRBP-II; CRBP2; RBPC2; CRBPII; CRABP-II
Tractability: Small molecule: a structure with a bound ligand is known; it has a binding pocket of medium quality.
Gene: Protein-coding gene on chromosome 3 (139,452,884 to 139,480,767, reverse strand). Ensembl gene ENSG00000114113.
Subcellular location: Cytoplasm
Subcellular location (Human Protein Atlas): Golgi apparatus
Pathways (Reactome):
Sensory Perception: Retinoid metabolism and transport
Gene Ontology:
Molecular function: all-trans-retinol binding; fatty acid binding; molecular carrier activity; retinoid binding; lipid binding; retinol binding; transmembrane transporter binding
Biological process: epidermis development; fatty acid transport; retinoid metabolic process; vitamin A metabolic process
Cellular component: cytosol; nucleus; cytoplasm; synaptic ribbon
Genetic constraint (gnomAD): Loss-of-function variants: 17 observed, 18.13 expected, observed/expected ratio (o/e) 0.94, 90% interval 0.64 to 1.41. The upper end of that interval is the gene's LOEUF score, 1.41, which puts it in group 5 of 6, group 1 being the genes least tolerant of losing a copy. Missense variants: 158 observed, 177.56 expected, observed/expected ratio (o/e) 0.89, 90% interval 0.78 to 1.01. Synonymous variants: 48 observed, 60.47 expected, observed/expected ratio (o/e) 0.79, 90% interval 0.63 to 1.01.
Homologues: Orthologues: chimpanzee RBP2 (98% identical), macaque RBP2 (97% identical), mouse Rbp2 (90% identical), guinea pig RBP2 (90% identical), rat Rbp1 (90% identical), rabbit RBP2 (88% identical), dog RBP2 (81% identical), pig RBP2 (80% identical), zebrafish rbp2a (75% identical), tropical clawed frog rbp2 (73% identical), zebrafish rbp2b (65% identical), Drosophila melanogaster fabp (31% identical), and 2 more. Paralogues in human: RBP7 (59% identical), RBP1 (55% identical), RBP5 (51% identical), FABP3 (40% identical), FABP4 (40% identical), FABP7 (38% identical), PMP2 (37% identical), FABP9 (36% identical), FABP12 (33% identical), CRABP1 (30% identical), CRABP2 (29% identical), FABP6 (28% identical), and 3 more.
Diseases named in the same sentence as RBP2 in open-access papers:
RBP2 is named in the same sentence as 45 diseases in open-access papers, as found by Europe PMC text mining. Sharing a sentence is not in itself a finding about the gene and the disease. The quoted sentences say what the papers report.
gastric cancer (14 papers, 2013 to 2022). A primary or metastatic malignant neoplasm involving the stomach. "In the present study, we sought to determine the potential role of RBP2 in human gastric cancer angiogenesis via the regulation of VEGF and the underlying mechanisms in vivo and in vitro." (PMID 24716659, 2014). "Recently, RBP2 was identified as one chromatin-modifying enzyme that participates in the carcinogenesis and progression of human cancers such as lung cancer, gastric cancer and breast cancer." (PMID 27008505, 2016). "Reversely, when RBP2 was overexpressed in gastric cancer cell lines, Snail-1 protein increased whereas E-cadherin decreased, confirming the role of RBP2 in the regulation of EMT-related genes expression." (PMID 25974964, 2015). "Third, VEGF expression induced by RBP2 overexpression activated tumorigenesis and angiogenic potential in human gastric cancer cells and animal models, whereas silencing of RBP2 expression had the reverse effect." (PMID 24716659, 2014). "As compared with normal human tissues, gastric cancer specimens showed overexpression of RBP2 and VEGF mRNA and the correlation of mRNA expression, which supports the role of RBP2 and VEGF in tumorgenesis and their co-expression in vivo." (PMID 24716659, 2014). "This clinical evidence supports the association of RBP2 and VEGF expression and increased angiogenesis in gastric cancer." (PMID 24716659, 2014). "RBP2 overexpression significantly affected VEGF expression in gastric cancer cells via demethylation of H3K4." (PMID 24716659, 2014). "Previous studies demonstrated that the oncogenic protein RBP2 was overexpressed in gastric cancer and NSCLC, which correlated with tumor senescence, proliferation, migration and invasion." (PMID 25162518, 2014). "First, we determined the association of RBP2 expression, VEGF expression and MVD status in human gastric cancer tissue species." (PMID 24716659, 2014). "In nude mice, tumors from transfected gastric cancer cells stably expressing RBP2 shRNA were smaller, with lower VEGF expression, and less MVD and cell proliferation than control cells." (PMID 24716659, 2014). "In our previous work, we found the high expression of RBP2 in gastric cancer (GC) as well as in hepatocellular carcinoma (HCC), and its inhibition can trigger cell senescence." (PMID 25015565, 2014). "We used western blot analysis to determine RBP2 and VEGF expression in gastric cancer cells with RBP2 silencing or VEGF overexpression." (PMID 24716659, 2014). "In gastric cancer, RBP2 binds to the promoter regions of the p16ink4a, p21CIP1 and p27kip1 genes to inhibit their expressions and diminish the senescence of cancer cells." (PMID 24376841, 2013). "For instance, the Retinoblastoma (Rb)-1 tumor suppressor gene is the target of miR-212 in PDAC (increased miR-212 suppresses Rb1 that promotes cell growth), but Rb binding protein-2 (RBP2) is the target in gastric carcinoma and HCC (decreased miR-212 upregulates RBP2 which promotes cell growth)." (PMID 35473623, 2022). "KDM5A, also known as retinoblastoma binding protein (RBP2), was initially identified as a binding partner of retinoblastoma protein, and its overexpression has been observed in cancers such as glioblastoma, gastric cancer, hepatocellular carcinoma, and lung cancer." (PMID 33578894, 2021). "We have shown that RBP2 promoted the initiation and progression of gastric cancer." (PMID 27008505, 2016). "In addition, we depleted RBP2 expression in undifferentiated gastric cancer cells (HGC-27) which exhibit spindle-, fibroblast-like morphology." (PMID 25974964, 2015). "We collected 130 cases of primary gastric cancer specimen and analyzed RBP2 expression there." (PMID 25974964, 2015). "Our group has evidenced the high expression of RBP2 in primary gastric cancer tissues, however, whether RBP2 expression correlated with tumor progression remained unclear." (PMID 25974964, 2015).
gastric cancer (continued). "In addition, we also detected TGFβRI which mediated the phosphorylation of Smad3 and was required for RBP2 upregulation in response to TGF-β1 in gastric cancer specimen." (PMID 25974964, 2015). "Furthermore, we also overexpressed RBP2 in gastric cancer cell lines and found their enhanced ability to migrate." (PMID 25974964, 2015). "Indeed, at least one of these enzymes is strictly associated with human cancer: KDM5A (also known as RBP2 and JARID1A) is over-expressed in gastric cancer, and its inhibition triggers cellular senescence of gastric cancer cells." (PMID 24489688, 2014). "To obtain direct evidence of whether RBP2 regulated the expression of VEGF and was involved in the angiogenesis of gastric cancer, we transfected RBP2 expression vector and siRNA into BGC-823, SGC-7901 and GES-1 cells." (PMID 24716659, 2014). "As well, RBP2 expression was involved in VEGF promoter activity in gastric cancer cells." (PMID 24716659, 2014). "For instance, the overexpression of RBP2 inhibits the senescence of gastric cancer cells." (PMID 24376841, 2013). "We found RBP2 overexpressed in gastric cancer, and its inhibition could trigger cancer-cell senescence." (PMID 23922798, 2013). "The H3K4 demethylase retinoblastoma binding protein 2 (RBP2) is involved in the pathogenesis of gastric cancer, but its role and regulation in hepatocellular carcinoma (HCC) is unknown." (PMID 23922798, 2013). "RBP2 is involved in the pathogenesis of gastric cancer, but its role and regulation in HCC was unknown." (PMID 23922798, 2013). "Here, we demonstrated that the histone demethylase RBP2 was crucial for TGF-β1-(p-Smad3)-RBP2-E-cadherin-Smad3 feedback circuit that was implicated in malignant progression of tumors and its knockdown significantly inhibited gastric cancer (GC) metastasis both in vitro and in vivo." (PMID 25974964, 2015). "Further data indicate that knockdown of endogenous RBP2 dominantly inhibits gastric cancer (GC) development both in vitro and in vivo." (PMID 25015565, 2014). "In gastric cancer cells, TGF-β, via SMAD3, stimulates the expression of the histone demethylase RBP2, which reciprocally augments SMAD3 activity." (PMID 34249916, 2021). "In this study, we focused on the critical role of the histone H3K4 demethylase RBP2 in angiogenesis of gastric cancer, especially the direct regulation of VEGF by RBP2." (PMID 24716659, 2014). "Second, we detected the direct regulation of VEGF by RBP2 both in human gastric cancer cell lines and RBP2-targeted mutant mice, which showed that H3K4 demethylation by RBP2 expression was important for VEGF expression and MVD status." (PMID 24716659, 2014). "The expression of RBP2, VEGF, CD31, CD34 and Ki67 was assessed in 30 human gastric cancer samples and normal control samples." (PMID 24716659, 2014). "The clone formation of human gastric cancer cells was also suppressed in this process, which was partially reversed by the overexpression of VEGF in RBP2 siRNA-transfected cells." (PMID 24716659, 2014). "RBP2 and VEGF were both overexpressed in human gastric cancer tissue, with greater microvessel density (MVD) and cell proliferation as compared with normal tissue." (PMID 24716659, 2014). "Our study identified a novel molecular mechanism for RBP2 and provides better understanding of the molecular basis for angiogenetic signaling pathways, which might aid in the design of effective therapeutic modalities to control gastric cancer growth and metastasis." (PMID 24716659, 2014). "We first investigated the expression of RBP2 in human HCC and found the same expression as in gastric cancer." (PMID 23922798, 2013). "We have previously shown that RBP2, an H3K4 demethylase on di- and tri- methylation, could regulate the expression of miR-21 in gastric cancer." (PMID 27086911, 2016). "Not as the suppression of CDKIs promoters by RBP2 in gastric cancer, RBP2 induced the activation of VEGF promoter by directly binding to the CCGCCC DNA motif." (PMID 24716659, 2014).
gastric cancer (continued). "Overexpression of RBP2 and activation of VEGF might play important roles in human gastric cancer development and progression." (PMID 24716659, 2014). "Therefore, abnormal RBP2 expression and VEGF activation might explain the poor prognosis with gastric cancer and contribute directly to gastric tumor angiogenesis and aggressive gastric cancer biology." (PMID 24716659, 2014). "However, we need more evidence to determine whether RBP2 affects the VEGF promoter methylation status, which is involved in the regulation of VEGF expression in human gastric cancer cells." (PMID 24716659, 2014).
lung carcinoma (10 papers, 2013 to 2025). "It has been demonstrated that RBP2 is overexpressed in lung cancer, and its expression is highly associated with cancer cell proliferation, invasion, migration and drug tolerance." (PMID 24376841, 2013). "RBP2 is overexpressed in human lung cancer tissues and is necessary for lung cancer cell proliferation, movement, migration, invasion, and metastasis." (PMID 35013450, 2022). "The protein level of RBP2 was up-regulated in lung cancer cell lines SK-MES-1, A549, SPCA-1 and H1975 compared to the human bronchial epithelial cell line BEAS2B." (PMID 25162518, 2014). "Published data showed that Cyclin D1 was a downstream target of RBP2 in lung cancer, so we tried to testify this in GC." (PMID 25015565, 2014). "Recent research in lung cancer has established that RBP2 is correlated to tumor migration and invasion by directly binding to integrin β1 (ITGB1) promoters." (PMID 25162518, 2014). "To study the roles of RBP2 in lung cancer, we first detected the expression of RBP2 in NSCLC tissues and their corresponding normal tissues using immunohistochemistry." (PMID 24376841, 2013). "In lung cancer, RBP2 binds to the promoter region of p27, cyclin D1 and integrin β1 to mediate cancer cell proliferation and metastasis." (PMID 24376841, 2013). "The levels of RBP2 in 10 lung cancer tissues and their corresponding normal lung tissues were further detected using western blot and real-time PCR analyses." (PMID 24376841, 2013). "The results showed that both RBP2 protein and mRNA were increased in the lung cancer tissues." (PMID 24376841, 2013). "To explore the role of RBP2 in lung cancer metastasis, we investigated whether RBP2 regulates cellular migration." (PMID 24376841, 2013). "All of these studies indicate that RBP2 is a potential target for anti-lung cancer therapy." (PMID 24376841, 2013). "In addition, RBP2 is involved in the carcinogenesis and progression of lung cancer." (PMID 27008505, 2016). "Additionally, the effects of RBP2 on the migration of lung cancer cells were studied, and we found that RBP2 could enhance NSCLC cellular migration." (PMID 24376841, 2013). "Previous reports identified several different RBP2 target genes including the cell cycle regulators p16, p21 and p27 in non-NET gastric and lung cancer." (PMID 27548814, 2016).
breast carcinoma (4 papers, 2010 to 2023). "RBP2 is also critical for breast cancer progression and metastasis." (PMID 27008505, 2016).
leukemia (3 papers, 2015 to 2021). A malignant (clonal) hematologic disorder, involving hematopoietic stem cells and characterized by the presence of primitive or atypical myeloid or lymphoid cells in the bone marrow and the blood. "Mechanistically, miR-181d downregulated the level of histone demethylase RBP2, which inhibited p65 expression in leukemia cells by its binding to the p65 promoter and demethylating the tri/dimethylated H3K4 region in the p65 promoter locus." (PMID 33842368, 2021). "Here, focus on epigenetic dysregulation, we revealed a new mechanism and showed that miR-181d promotes leukemia cell proliferation by directly targeting and negatively regulating the histone demethylase RBP2." (PMID 33842368, 2021). "Thus, RBP2 might serve as a potential diagnostic marker for different types of leukemia." (PMID 27008505, 2016). "We determined the requirement for RBP2 in differentiation of leukemia cells by inducing granulocytic differentiation in vitro." (PMID 25575817, 2015). "The RBP2 histone demethylase stimulates leukemia cell differentiation and inhibits cell proliferation." (PMID 25575817, 2015). "We explored the potential role of RBP2 in leukemia cell proliferation by transfecting RBP2 expression plasmid into K562 and HL60 cells." (PMID 25575817, 2015). "We identified miR-21 was directly downregulated by RBP2 and found that miR-21 downregulated PDCD4 expression in leukemia cells." (PMID 25575817, 2015).
melanoma (3 papers, 2011 to 2015). A malignant, usually aggressive tumor composed of atypical, neoplastic melanocytes. "Using esophageal cancer cells, we investigated the functional roles of the H3K4 demethylase Jumonji/Arid1b (Jarid1b) (Kdm5b/Plu-1/Rbp2-h1), an epigenetic factor that is required for continuous cell growth in melanoma." (PMID 24649241, 2013). "Through the use of H3K4 demethylase Jarid1b (Kdm5b/Plu-1/Rbp2-h1) as a biomarker, a small subpopulation of tumor-initiating melanoma cells was isolated." (PMID 24649241, 2013). "Among these proteins, RBP2 mediates drug resistance while JARID1B is required for melanoma maintenance." (PMID 21544224, 2011). "In addition, RBP2 induction is one of the five major traits of drug-tolerant subpopulation (cancer stem cells) in melanoma." (PMID 25974964, 2015). "Specific to the KDM5 family proteins, drug resistant cells overexpressing RBP2 seem to have some features found in cancer stem cells and JARID1B marks a subpopulation of human melanoma cells that can sustain tumor growth and self renewal, suggesting a new definition of melanoma stem cells." (PMID 21544224, 2011).
non-small cell lung carcinoma (3 papers, 2013 to 2024). A group of at least three distinct histological types of lung cancer, including non-small cell squamous cell carcinoma, adenocarcinoma, and large cell carcinoma. "In this study, we analyzed the effects of RBP2 on epithelial-mesenchymal transition in non-small cell lung cancer." (PMID 24376841, 2013).
small cell lung carcinoma (3 papers, 2021 to 2025). Small cell lung cancer (SCLC) is a highly aggressive malignant neoplasm, accounting for 10-15% of lung cancer cases, characterized byrapid growth, and early metastasis. "KDM5A/RBP2 is a demethylase that suppresses NOTCH signaling, sustains neuroendocrine differentiation, and facilitates the development of small-cell lung cancer." (PMID 40282196, 2025). "RBP2 histone demethylase suppresses NOTCH signaling to sustain neuroendocrine differentiation and promote small cell lung cancer tumorigenesis." (PMID 35205261, 2022).
renal cell carcinoma (2 papers, 2021). "Retinoblastoma-Binding Protein 2 (RBP2) is a histone demethylase over-expressed in HCC, and RBP2 can induce CSC phenotypes through converting renal cell carcinoma cells into a more mesenchymal phenotype." (PMID 34147074, 2021).
thyroid cancer (2 papers, 2022 to 2025). "RBP2 exhibited significant downregulation across several tumors, including KICH, KIRC, KIRP, LUAD, LUSC, and thyroid carcinoma (THCA), with elevated expression observed in breast invasive carcinoma (BRCA), cholangiocarcinoma (CHOL), colon adenocarcinoma (COAD), and LIHC." (PMID 41301068, 2025).
adenoma (1 paper, 2019). A neoplasm arising from the epithelium. "Therefore, downregulation of RBP2 indicates that decreased ATRA production may play a role in the transition of normal duodenum to adenoma." (PMID 31211760, 2019). "In adenoma-normal, downregulation of DEGs involved in metabolism of brush border proteins (LCT), lipids (APOB/A4), reactive oxygen species (GSTA2), and retinol (RBP2) was observed." (PMID 31211760, 2019).
carcinoid (1 paper, 2016). "RBP2 was detected in the cytoplasm of the well-differentiated tumor cells (carcinoid), but in the nucleus of poorly differentiated cells (liver met)." (PMID 27548814, 2016).
cervical tumors (1 paper, 2005). "Microarray analysis identified among the most prevalent alterations in cervical tumors and cell lines the amplification of the RBP1- RBP2 (Retinol binding protein 1 and 2, 58.8%) and Tp63 (52.9% of the samples) genes, located at 3q21-q22 and 3q27-q29, respectively." (PMID 16004614, 2005).
COVID-19 (1 paper, 2023). A disease caused by infection with severe acute respiratory syndrome coronavirus 2. "We found elevated plasma RBP2 in patients with COVID-19 with comorbidities compared to the HCs as well as to their DCs, but no significant changes were observed in patients without comorbidities vs. HCs." (PMID 37047248, 2023). "Importantly, several unreported elevated proteins in patients with COVID-19, such as RBP2 and BST2, which show anti-microbial activity, along with proteins involved in extracellular matrix remodeling, including MATN2 and COL6A3, were identified." (PMID 37047248, 2023).
gastric tumor (1 paper, 2014). "To further identify the mechanisms involved in RBP2-associated gastric tumor growth, we examined the effect of RBP2 expression on VEGF expression and tumor angiogenesis in nude mice." (PMID 24716659, 2014). "In contrast with the large tumors produced by control cells, RBP2-shRNA–transfected BGC-823 cells produced much smaller gastric tumors with slower growth." (PMID 24716659, 2014). "We established stable lentiviral-RBP2-shRNA–transfected BGC-823 cells and injected them into the subcutis of nude mice to evaluate the effect of knockdown of RBP2 expression on gastric tumor growth and angiogenesis by regulating VEGF expression." (PMID 24716659, 2014). "Our new findings that RBP2 is critical in constitutive and inducible VEGF expression might suggest its clinical implication in gastric tumor angiogenesis and progression." (PMID 24716659, 2014).